VWF (von Willebrand factor)
Diseases named in the same sentence as VWF in open-access papers (continued):
Sharing a sentence is not in itself a finding about the gene and the disease.
endothelial dysfunction (continued). "On the other hand, anthocyanin caused a slight increase in BG (+0.14, p = 0.024 vs. placebo) and the von Willebrand factor, a marker of endothelial dysfunction (+5%, p = 0.007 vs. placebo)." (PMID 35955475, 2022). "Along the same line, high levels of markers of endothelial dysfunction such as vWF, P-selectin, and vascular cell adhesion protein (VCAM-1) are found in DVT patients." (PMID 35574486, 2022). "Hypoxia also induces exocytosis of Weibel-Palade bodies (WPb) from ECs, which contain von Willebrand Factor (vWF) and clinical studies suggest that increased plasma vWF is a biomarker of endothelial dysfunction in cardiovascular disease." (PMID 35250627, 2022). "The link between inflammation and endothelial dysfunction in cardiovascular disease is well-established; vWF is key in this process where it is secreted into the circulation from endothelial cells in response to systemic inflammation." (PMID 36291628, 2022). "In fact, atrial dilation and volume overload of the left atrial appendage are associated with increased endocardial expression of the glycoprotein von Willebrand Factor (vWF), a well-documented marker of endothelial dysfunction." (PMID 36230924, 2022). "Remarkably, in patients with COVID-19 admitted to the ICU, increased levels of von Willebrand Factor (vWF) antigen and P-selectin in plasma were detected, indicating endothelial dysfunction." (PMID 35431989, 2022). "In patients with GDM, an elevated expression of VWF and reduced expression of AT in plasma suggest endothelial injury and endothelial dysfunction." (PMID 36080270, 2022). "Patients with cirrhosis experience endothelial dysfunction in the hepatic vascular bed, which contributes to the release of vWF in activated endothelial cells; therefore, endothelial dysfunction is considered a major determinant of increased vWF-Ag levels." (PMID 35360443, 2022). "Elevated expression of VWF and reduced expression of AT in plasma suggest endothelial injury and endothelial dysfunction." (PMID 36080270, 2022). "Along with von Willebrand factor (which acts as its carrier protein), its role has been discussed in endothelial dysfunction and atherosclerosis." (PMID 36142883, 2022). "SARS-CoV-2-Induced endothelial damage releases a variety of soluble markers of endothelial dysfunction, including von Willebrand factor (VWF), soluble E-selectin, P-selectin and thrombomodulin." (PMID 36522776, 2022). "It was previously shown that vWF activity represents endothelial dysfunction and is along with factor VIII are significantly increased after hypoglycaemia." (PMID 35596173, 2022). "As a result of endothelial dysfunction, tissue factor and von Willebrand factor (vWF) are released into the blood stream, which leads to prothrombinase activation." (PMID 35887770, 2022). "Inflammatory reaction causes endothelial dysfunction, leading to increased production of thromboxane A2 (TXA2), von Willebrand factor (vWF), and thrombin, which are potent platelet agonists." (PMID 35432313, 2022). "During the inflammatory activation associated with COVID-19, the vascular imbalance of VWF and ADAMTS13 favors an elevated VWF:AG/ADAMTS13 activity ratio; this shift is implicated in localized endothelial dysfunction of COVID-19 infection." (PMID 35087853, 2021). "Consistently, biomarkers of endothelial dysfunction, such as thrombomodulin, VWF, angiopoietin 2, and plasminogen activator inhibitor-1, are frequently elevated, and seem to be associated with disease severity in COVID-19 patients." (PMID 34769508, 2021). "There is a relationship between vWF and the amount of visceral fat that produces adipokines responsible for endothelial dysfunction." (PMID 34207297, 2021). "Whereas most proteins induced significant changes in endothelial permeability, nsp2, nsp5_c145a (catalytic dead mutant of nsp5), and nsp7 also reduced CD31, and increased von Willebrand factor expression and IL-6, suggesting endothelial dysfunction." (PMID 34694226, 2021).
endothelial dysfunction (continued). "Most patients at thrombosis risk exhibit endothelial dysfunction, which manifests in loss of protective molecules and expression of adhesive molecules, and increased secretion of PAI-1 and vWF." (PMID 32529549, 2021). "Increased RAS activity (renin), endothelial dysfunction (vWF), coagulation parameters (D-dimer, prothrombin fragment F1,2) and inflammation (CRP, IL-6) were significantly altered in COVID patients and followed similar trends from mild-COVID to ARDS-COVID." (PMID 34945736, 2021). "Following endothelial dysfunction, this stored VWF is secreted, providing an effective bridge for platelet aggregation and thrombus assembly, which is conducive to the formation of organized clots." (PMID 34064553, 2021). "For the first time, vWF, a biomarker of endothelial dysfunction, together with neutrophil count and PaO2/FiO2 was included into a risk assessment model for prediction of in-hospital mortality." (PMID 34235394, 2021). "Another approach is the measurement in blood concentration of biomarkers reflecting endothelial dysfunction, such as soluble vascular adhesion molecule-1, soluble E-selectin, or von Willebrand factor (vWF)." (PMID 33641611, 2021). "This is partly attributable to endothelial dysfunction, resulting in reduction in nitric oxide and prostacyclin synthesis and increased release of vWF." (PMID 32529549, 2021). "VWF, an indicator of endothelial dysfunction, is the first step in mediated adhesion of platelets to damaged endothelial cells in thrombus formation." (PMID 34690744, 2021). "The involvement of VWF in local vascular injury and homeostasis lends itself to being a key determinant of endothelial dysfunction, and thus cardiac failure pathogenesis." (PMID 34564132, 2021). "Several studies have indicated that elevated expression of vWF in plasma suggests endothelial injury and endothelial dysfunction." (PMID 34777257, 2021). "Aging and obesity independently contribute toward an endothelial dysfunction that results in an imbalanced VWF to ADAMTS13 ratio." (PMID 35087853, 2021). "The increase in VWF levels and binding activity are consistent with endothelial dysfunction in patients <65 years of age." (PMID 35087853, 2021). "In this study, dabigatran increased the expression of vWF, which led to inflammation, endothelial dysfunction, and oxidative stress." (PMID 34603033, 2021). "We detected the levels of vWF, a well-known marker of endothelial dysfunction, in culture supernatant under sFlt-1 challenge." (PMID 32790760, 2020). "The polymeric IgA1 complex appeared to act directly on sFlt-1, and the latter further stimulated the production of endothelial cells injury marker of vWF, contributing the endothelial dysfunction in IgAN." (PMID 32790760, 2020). "The differentiation of monocytes into endothelial cells, expressing vWF, was also induced in murine aortas ex vivo, after endothelial dysfunction induced by LPS and LPA." (PMID 31906296, 2020). "There was an inverse association between choroidal thickness and circulating markers of endothelial dysfunction (endothelin-1 r = −0.49, p ≤ 0.001; von Willebrand factor r = −0.32, p ≤ 0.05)." (PMID 33080821, 2020). "The stored vWF is rapidly released at moments of endothelial cell damage, thus it is considered as a promised biomarker for endothelial dysfunction." (PMID 32039706, 2020). "Numerous studies have demonstrated the relationship between elevated vWF levels and endothelial dysfunction." (PMID 33118727, 2020). "The level of vWF was observably increased and P- selectin showed an increasing trend, indicating endothelial dysfunction in rat aorta." (PMID 32892299, 2020). "It is very well known that pathological levels (both decreased and increased levels) of fibrin(ogen), D-dimer, VWF and P-selectin play crucial roles in abnormal coagulation and endothelial dysfunction." (PMID 32708334, 2020).
endothelial dysfunction (continued). "Both the HDACs inhibitor trichostatin A and DF prevented the up‐regulation of the endothelial dysfunction markers induced by the uraemic milieu: intercellular adhesion molecule‐1, surface Toll‐like receptor‐4, von Willebrand Factor and reactive oxygen species." (PMID 31782253, 2020). "Flow-mediated dilation was measured together with the assessment of the values of endothelin-1, von Willebrand factor, and asymmetric dimethylarginine to identify endothelial dysfunction." (PMID 33118727, 2020). "The markers of endothelial dysfunction, VWF:Ac and VWF:Ag, were found to be decreased in the same population (p < 0.001), along with the vWF Ac/Ag ratio (p = 0.02)." (PMID 32992591, 2020). "In line with this, we found the positive correlation between the biochemical marker for endothelial dysfunction, von Willebrand factor (vWF), and RANTES level." (PMID 31321561, 2019). "In BD, increased thromboembolism is triggered due to endothelial dysfunction, von Willebrand factor release, platelet activation, increased thrombin and fibrin release, and antithrombin deficiency." (PMID 31241876, 2019). "vWF levels increase following endothelial damage, and this factor is used as a marker of endothelial dysfunction, which is an important early process in atherosclerosis development." (PMID 29409455, 2018). "Serum magnesium related inversely to prevalent AF, lung function (FEV1) and markers of inflammation (IL-6), endothelial dysfunction (vWF) and cardiac dysfunction (cTnT, NT-proBNP), all markers of pathways involved in the pathogenesis of HF." (PMID 29663176, 2018). "One important finding of our study is that patients with low BDNF levels exhibited increased vWF levels, which potentially reflects endothelial dysfunction." (PMID 29409455, 2018). "It was verified that the decline of GFR also results in endothelial dysfunction and the release of the von Willebrand factor, which promotes platelet adhesion and aggregation and, consequently, microthrombi formation and increased D-Dimer levels." (PMID 29694626, 2018). "Circulating vWF levels are an easy-to-measure, readily available parameter of endothelial dysfunction that requires only blood samples." (PMID 29409455, 2018). "For example, one can look at the blood level of von Willebrand factor (vWF) as an indication of endothelial dysfunction." (PMID 28100233, 2017). "We found previously that MSZR presented endothelial dysfunction as shown by increased circulating VWF." (PMID 29213245, 2017). "Endothelial dysfunction probably represents the background that links VWF, inflammation, and thrombosis." (PMID 28634421, 2017). "The present study confirmed that the markers of endothelial dysfunction like vWF, TM, sICAM-1, and sVCAM-1 were markedly elevated in the plasma of CKD group compared to controls." (PMID 28122514, 2017). "This endothelial dysfunction was exacerbated during aging as shown by increases in both VWF and soluble CD146." (PMID 29213245, 2017). "Since damage to endothelial cells leads to an increase in the level of circulating vWF, the latter is a suitable marker of endothelial dysfunction." (PMID 26885523, 2016). "In the present study, group BI showed an elevated level of vWF activity after injury, thereby proving the occurrence of endothelial dysfunction in cases of burn injury combined with seawater immersion." (PMID 26885523, 2016). "Three endothelial dysfunction markers, vWF, ITGβ1 and GP1βA were down-regulated by NaHS treatment compared with type II diabetes both in vivo and in vitro." (PMID 27222705, 2016). "This is consistent with the findings that copeptin correlated significantly with inflammation and with vWF and tPA (markers of endothelial dysfunction) independently of insulin resistance." (PMID 26158609, 2015). "Von willebrand factor (VWF), another potential marker of endothelial dysfunction produced by endothelial cells and platelets, is elevated in patients with non-pulmonary sepsis who go on to develop ARDS." (PMID 26652251, 2015).
endothelial dysfunction (continued). "In addition, our study found that FMD was moderately correlated with endothelium-mediated pro-inflammatory and pro-thrombotic molecules, including sVCAM-1, sE-selectin, and vWF, which suggests that NO deficiency may co-exist with other pathogenesis of endothelial dysfunction in patients with CKD." (PMID 26132137, 2015). "cfDNA levels correlated with markers of endothelial dysfunction (hsCRP P = 0.0497) and vWF (P = 0.0005)." (PMID 25371664, 2014). "Patients with RA of short duration exhibited biochemical indices of endothelial dysfunction that is highly significantly increased levels of vWf, MCP-1, and sVCAM-1." (PMID 24864133, 2014). "To this end, we included young individuals below the age of 35 years to exclude the presence of extensive atherosclerosis, which is related to endothelial dysfunction and consequent higher VWF:Ag levels." (PMID 24626470, 2014). "vWF is a protein found in the endothelium that plays an essential role in platelet adhesion, and functions as a biomarker for endothelial dysfunction and damage." (PMID 23866777, 2013). "It is known that vWF is a marker of endothelial dysfunction and widely used to study angiogenesis in cancer and ocular diseases." (PMID 24499599, 2013). "Plasma vWF is regarded as a good indicator of endothelial dysfunction and has been shown to contribute to the activation of the coagulation cascade." (PMID 24137281, 2013). "In line with this, increased vWF levels have been discussed as a biomarker for endothelial dysfunction in pulmonary arterial hypertension." (PMID 23056262, 2012). "The relationship between vWF and endothelial dysfunction has been extensively studied, and is thought to be due to release of vWF from the endothelium into the circulation upon endothelial damage or activation." (PMID 28352406, 2012). "Von Willebrand factor (vWF), P-selectin, and 8-iso-PGF2a have also been identified as surrogate markers of endothelial dysfunction and levels of these factors are increased in patients with cirrhosis compared with controls." (PMID 22720166, 2012). "vWF is increased in subjects with CKD, and it is considered to be a marker for endothelial dysfunction and CVD risk." (PMID 21269477, 2011). "Endothelial activation (soluble vascular cellular adhesion molecule-1) sVCAM-1, von Willebrand factor (vWF), thrombomodulin), endothelial dysfunction (determined by small artery elasticity (SAE)) and IMT were measured and related to AGE accumulation." (PMID 22168993, 2011). "Neither the carbon load of macrophages nor the distance from residence to major roads, were associated with plasma von Willebrand factor or PAI-1, taken as indices of endothelial dysfunction." (PMID 21283820, 2011). "There is a strong relation between CECs and endothelial dysfunction because numbers of CECs correlate with surrogate markers of disturbed endothelial function such as flow-mediated dilation and von Willebrand factor (vWF)." (PMID 20525353, 2010). "We also evaluated VWF antigen levels, which is increased in patients with sepsis, and is an indicator of endothelial dysfunction and stimulation." (PMID 20509945, 2010). "The serum level of vWF, a sensitive marker of endothelial dysfunction was higher in the patients on HD with CVD than in those without." (PMID 20535268, 2010). "Increased numbers of CECs, considered detached dysfunctional endothelial cells, are associated with endothelial damage in various vascular diseases and correlate with plasma markers (i.e. von Willebrand factor, soluble E-selectin) of endothelial dysfunction." (PMID 20485543, 2010). "Plasma levels of vWF have been considered as a marker of endothelial dysfunction and damage, although this is controversial and results from studies that have correlated plasma levels of vWF, severity of inflammation and patient outcome are inconsistent." (PMID 19538758, 2009).
endothelial dysfunction (continued). "Increase in Von-willebrand factor antigen, endothelial dysfunction, alterations of clotting cascade, thromboxane-prostacyclin homeostatic disturbances, and stimulation of fibroblasts add to the propensity of thrombotic events with cisplatin." (PMID 20062719, 2009). "We sought to define the relationship between ECLT, as a marker of fibrinolysis, von Willebrand factor (vWF), a marker of endothelial dysfunction, and the severity of the clinical syndrome in critically ill patients." (PMID 19538758, 2009). "Endothelial dysfunction biomarkers including von Willebrand factor, VCAM-1 and thrombomodulin, as well as the soluble form of CX3CL1 were measured by enzyme-linked immunosorbent assays (ELISA)." (PMID 19587779, 2009). "The increase of many markers of endothelial dysfunction, including thrombomodulin, von Willebrand factor (VWF) and VCAM-1, has been repeatedly reported in women with PE." (PMID 19587779, 2009). "This was confirmed by massive accumulation of smooth muscle cells with a high proliferation rate and endothelial perturbation and an increase of von Willebrand factor as an indictor of endothelial dysfunction." (PMID 18445288, 2008). "The protease, a disintegrin and metalloproteinase with thrombospondin type 1 motif member 13 (ADAMTS13), known to cleave only the von Willebrand factor (VWF), has powerful regulatory effects on microvascular platelet adhesion, thrombosis, inflammation, and endothelial dysfunction." (PMID 39851513, 2025). "Furthermore, endothelial dysfunction cascade: Chronic HUA reduces nitric oxide bioavailability by 62% while elevating von Willebrand factor (vWF) levels 2.3-fold, collectively promoting atherosclerotic plaque formation (annual volume growth rate +22.4%)." (PMID 41141353, 2025). "For example, silencing of endothelial vWF has been shown to reduce angiotensin II–induced endothelin‐1 expression, suggesting that a LEF1‐vWF‐ET‐1 axis might contribute to endothelial dysfunction in AAA." (PMID 41208012, 2025). "VWF levels may correlate with the degree of endothelial dysfunction in this chronic inflammatory state, which would increase thrombosis even further." (PMID 40362344, 2025). "Biomarkers such as von Willebrand factor, while additive, lack liver specificity and may be confounded by systemic endothelial dysfunction in heart failure or sepsis, thereby lowering specificity." (PMID 40861225, 2025). "Endothelial dysfunction is an additional pertinent element of Virchow’s triad that has been identified in patients with AF through the measurement of various markers of endothelial perturbation, including von Willebrand factor and E-selectin." (PMID 40158072, 2025). "Aging contributes to endothelial dysfunction, affecting the balance between vWF and ADAMTS1338." (PMID 40251396, 2025). "Elevated levels of complement-related markers such as von Willebrand factor, thrombomodulin, and angiopoietin-2 are frequently observed in patients with severe COVID-19, underscoring the link between complement activation, endothelial dysfunction, and thrombotic complications." (PMID 41458994, 2025). "Mechanistically, elevated vWF levels in CAD likely mirror endothelial dysfunction." (PMID 41007843, 2025). "While vWF elevation may initially reflect endothelial dysfunction and injury, emerging evidence suggests it also plays an active causal role in inflammatory processes." (PMID 41007843, 2025). "Furthermore, imbalanced expression of endothelin-1, tissue plasminogen activator (tPA), plasminogen activator inhibitor-1 (PAI-1), and von Willebrand factor (vWF) are also characteristic of endothelial dysfunction." (PMID 40650261, 2025). "Proteins like VWF, although primarily involved in hemostasis, may also reflect endothelial dysfunctions exacerbated by metabolic disturbances." (PMID 38825675, 2024).